CLYBL (citramalyl-CoA lyase)
Description:
Mitochondrial enzyme required to detoxify vitamin B12-poisoning metabolites. Acts as a citramalyl-CoA lyase by converting citramalyl-CoA into acetyl-CoA and pyruvate in the C5-dicarboxylate catabolism pathway, a pathway required to detoxify itaconate, a vitamin B12-poisoning metabolite. Also acts as a malyl-CoA thioesterase to detoxify malyl-CoA, a side product of citric acid cycle enzymes, which is toxic for the vitamin B12-dependent enzyme MMUT. Also acts as a malate synthase in vitro, converting glyoxylate and acetyl-CoA to malate. Also acts as a beta-methylmalate synthase in vitro, by mediating conversion of glyoxylate and propionyl-CoA to beta-methylmalate. Also has very weak citramalate synthase activity in vitro.
Synonyms: CLB
Tractability: Small molecule: a structure with a bound ligand is known. PROTAC: its protein half-life has been measured.
Gene: Protein-coding gene on chromosome 13 (99,606,641 to 99,909,459, forward strand). Ensembl gene ENSG00000125246.
Subcellular location: Mitochondrion
Gene Ontology:
Molecular function: (S)-citramalyl-CoA lyase activity; acyl-CoA hydrolase activity; magnesium ion binding; malate synthase activity; catalytic activity
Biological process: protein homotrimerization; regulation of cobalamin metabolic process; toxic metabolite repair; positive regulation of cobalamin metabolic process
Cellular component: mitochondrion
Genetic constraint (gnomAD): Loss-of-function variants: 26 observed, 30.41 expected, observed/expected ratio (o/e) 0.85, 90% interval 0.63 to 1.19. The upper end of that interval is the gene's LOEUF score, 1.19, which puts it in group 5 of 6, group 1 being the genes least tolerant of losing a copy. Missense variants: 353 observed, 336.38 expected, observed/expected ratio (o/e) 1.05, 90% interval 0.96 to 1.15. Synonymous variants: 146 observed, 133.02 expected, observed/expected ratio (o/e) 1.1, 90% interval 0.96 to 1.26.
Homologues: Orthologues: chimpanzee CLYBL (99% identical), dog CLYBL (91% identical), pig CLYBL (90% identical), guinea pig CLYBL (88% identical), macaque CLYBL (86% identical), mouse Clybl (86% identical), rat Clybl (84% identical), tropical clawed frog clybl (70% identical), rabbit CLYBL (67% identical), zebrafish clybl (64% identical).
Diseases named in the same sentence as CLYBL in open-access papers:
CLYBL is named in the same sentence as 13 diseases in open-access papers, as found by Europe PMC text mining. Sharing a sentence is not in itself a finding about the gene and the disease. The quoted sentences say what the papers report.
COVID-19 (2 papers, 2022 to 2025). A disease caused by infection with severe acute respiratory syndrome coronavirus 2. "Itaconic acid supplementation and CLYBL inhibition are possible therapeutic options for the treatment of COVID-19 that aim to modulate host defense to combat SARS-CoV-2 infection." (PMID 36163484, 2022). "A clinical study reported that CLYBL levels are increased in the macrophages of patients with COVID-19." (PMID 39863605, 2025). "A clinical study also reported increased levels of the macrophage-enriched enzyme CLYBL in patients with COVID-19." (PMID 39863605, 2025).
heart failure (1 paper, 2025). Inability of the heart to pump blood at an adequate rate to meet tissue metabolic requirements. "Additionally, under the condition of CLYBL hyperacetylation, the markedly upregulated heart failure markers ANP and BNP were observed in the mice treated with Ang II." (PMID 39863605, 2025).
teratoma (1 paper, 2015). A non-seminomatous germ cell tumor characterized by the presence of various tissues which correspond to the different germinal layers (endoderm, mesoderm, and ectoderm). "CLYBL-targeted human iPSC clones maintained stable reporter gene expression and normal karyotype, expressed pluripotency surface markers and were capable of differentiating into all three germ layers by in vitro embryoid body and in vivo teratoma assays." (PMID 25587899, 2015).
vitamin B12 deficiency (1 paper, 2026). A disease characterized by low serum levels of vitamin B12, either inherited or acquired. "Loss of CLYBL gene function has been associated with vitamin B12 deficiency." (PMID 41511364, 2026).
tumor (3 papers, 2020 to 2025). "In the TCGA_LIHC cohort, 16 of 120 genes were downregulated in HCC tissue rather than in adjacent non-tumor tissue, and 9 of 16 genes, namely, ALDH8A1, C11orf96, CLYBL, EFNB3, ENG, NPC1L1, PIM3, SEC14L2, and SLC8A1, displayed a significant difference (p < 0.05)." (PMID 33352935, 2020).
CLYBL also shares sentences with these, for which no sentence is quoted: infection (7 papers); cancer (4); tuberculosis (4); Sepsis (2); Diabetes (1); Dravet syndrome (1); liver cancer (1); Obesity (1).